PRPS2 (phosphoribosyl pyrophosphate synthetase 2)
Diseases named in the same sentence as PRPS2 in open-access papers (continued):
Sharing a sentence is not in itself a finding about the gene and the disease.
lung adenocarcinoma (1 paper, 2025). A carcinoma that arises from the lung and is characterized by the presence of malignant glandular epithelial cells. "To assess the oncogenic potential of PRPS isoforms, we initially compared the mRNA levels of PRPS1 and PRPS2 in 47 cases of lung adenocarcinoma specimens with paired adjacent normal tissues." (PMID 40295500, 2025). "Our analysis revealed a significant upregulation of PRPS2 mRNA levels in 38 cases (81%) of lung adenocarcinoma compared to their adjacent normal tissues, while no significant alteration was observed for PRPS1 mRNA levels." (PMID 40295500, 2025). "Consistent with the mRNA findings, endogenous PRPS2 protein expression was notably elevated in lung adenocarcinoma specimens compared to paired adjacent normal tissues." (PMID 40295500, 2025). "Further Kaplan-Meier analysis of clinicopathological specimens from the Cancer Genome Atlas (TCGA) and GEO databases confirmed the significant upregulation of PRPS2 expression, in lung adenocarcinoma specimens compared to adjacent normal tissues." (PMID 40295500, 2025). "In this study, we demonstrate that PRPS2, distinct from its highly inter-isoform conserved homolog PRPS1, promotes RNA m6A methylation in lung adenocarcinoma tumorigenesis through its canonical metabolic and non-metabolic functions." (PMID 40295500, 2025).
cancer (16 papers, 2016 to 2025). A tumor composed of atypical neoplastic, often pleomorphic cells that invade other tissues. "More recently, studies have also discovered that PRPS1 and PRPS2 are mutated in therapy-resistant relapsed ALL cancer patients." (PMID 32650483, 2020). "Previous studies suggest an association between PRPS2 and c-Myc-driven cancers." (PMID 34316327, 2021). "Human PRPS2 may well be an attractive diagnostic target for Myc-driven cancers in osteosarcoma." (PMID 35741038, 2022). "Strikingly, PRPS2 is specifically upregulated to enhance nucleotide and protein biosynthesis in cancer cells with oncogene c-Myc overexpression, and the knockout of PRPS2 is synthetically lethal to such cancer cells." (PMID 40295500, 2025). "PRPS2 expression varied among the cell lines, with 8 out of 12 cancer cell lines exhibiting high or moderate expression levels, while the normal lung fibroblast cell line showed undetectable low expression of PRPS2." (PMID 40295500, 2025). "Nevertheless, our results highlight the unique and indispensable role of PRPS2 serving as an essential “molecular rheostat” that links glucose metabolism to diverse metabolite biosynthesis pathways vital for cancer development." (PMID 40295500, 2025). "This positions PRPS2 as an intriguing anti-cancer drug target due to its distinct oncogenic functionality." (PMID 40295500, 2025). "Phosphoribosyl pyrophosphate synthetase 2 (PRPS2) has emerged as an oncogenic factor in various cancer types, supported by its documented involvement in promoting carcinogenesis." (PMID 38952044, 2024). "It has been found that PRPS1 and PRPS2 play important regulatory roles in different malignant tumors." (PMID 38736292, 2024). "Nonetheless, these findings enhance our comprehension of the regulatory mechanisms involved in immune cell recruitment in cancer and propose PRPS2 as a promising target for therapeutic interventions." (PMID 38952044, 2024). "The c-Myc-PRPS2 interaction promotes metabolic reprogramming of biosynthetic processes leading to the proliferation of cancer cells." (PMID 35741038, 2022). "PRPS2 is more responsive to the cellular concentration of ATP and loss of PRPS2 is synthetically lethal when MYC is overexpressed and, indeed, essential for Myc-driven cancer proliferation, but dispensable for normal physiology." (PMID 35741038, 2022). "Not only is PRPS2 expression regulated by Myc, but PRPS2-knockout mice are also resistant to Eμ–Myc-driven cancer development." (PMID 32650483, 2020). "PRPS2 produces nucleotide biosynthetic precursor, 5-phosphoribosyl-1-pyrophosphate, therefore, it is beneficial for cancer cell proliferation and survival if the expression of PRPS2 is elevated." (PMID 31671902, 2019). "Given that PRPS2 is only essential for cancer cells and is less expressed in normal tissues, such therapeutics may be more specific and exhibit fewer side effects." (PMID 40295500, 2025). "However, the orthogonal approaches for PRPS2 knockdown/knockout, including lentiviral CRISPR/gRNA, shRNA as well as siRNAs, are lethal to the cancer cell lines with high endogenous PRPS2 expression level, which is in consistent with previous findings." (PMID 40295500, 2025). "The translationally regulated enzyme PRPS2 may play a role in the proliferation of oncogenic signalling-driven cancers." (PMID 35741038, 2022). "PRPS2-knockout mice were generated in the context of a Myc-driven cancer model." (PMID 32650483, 2020). "ACSL6, PRPS1 and PRPS2 genes represent potential therapeutic targets to limit cancer cell growth using specific inhibitors, which could re-program cancer cell metabolism by reducing FA." (PMID 31434359, 2019). "Consequently, our study underscores the potential of targeting PRPS2 enzymatic activity to halt tumor growth and defines a valuable and vulnerable target in cancer metabolism, essential for proliferation across various cancer types." (PMID 40295500, 2025). "PRPS2 may be a promising diagnosis and therapy target for these cancers." (PMID 37248548, 2023).
cancer (continued). "The distinguishing features of the PRPS2 isoform are found in many translationally regulated transcripts because of mTOR hyperactivation, allowing nucleotide and protein biosynthesis to increase concomitantly with higher protein synthetic capacity protein of cancer cells." (PMID 35741038, 2022). "Therefore, the drugs specifically targeting PRPS2 or other enzymes involved in nucleotide biosynthesis may be important for metabolic reprogramming in anoikis-evading cancer cells." (PMID 33854965, 2021). "Furthermore, another Prps gene, Prps2, directly promotes cancer cell proliferation in mice." (PMID 27425195, 2016). "Moreover, in c‐Myc overexpressed cancer cells, the activated eukaryotic initiation factor 4E could bind with the pyrimidine‐rich translational element of PRPS2 mRNA to promote the translation of PRPS2 making the level of nucleotide metabolism up‐regulated." (PMID 32391636, 2020). "However, the canonical metabolic and non-metabolic functions of PRPS2 in cancer development remain elusive." (PMID 40295500, 2025). "PRPS2-knockout mice are viable and fertile with no discernible developmental defects, which supports the hypothesis that mPRPS2 is not essential for development but contributes to Myc-dependent cancer formation." (PMID 35741038, 2022). "Previous studies have highlighted the role of c-Myc in upregulating PRPS2, but not its highly conserved inter-isoform homolog PRPS1, to meet the specific high demands for nucleotide synthesis in cancer cells." (PMID 40295500, 2025).
tumor (16 papers, 2015 to 2026). "Previously, the expression levels of PRPS2 vary in different tumor tissues, and its related mechanism is preliminarily discussed." (PMID 38736292, 2024). "The use of clodronate liposomes and anti‐Gr‐1 antibody effectively reversed the phenotypic effects of PRPS2 overexpression, emphasizing the importance of TAM and MDSC in mediating the functions of PRPS2 in the tumor microenvironment." (PMID 38952044, 2024). "Herein, we modulated the expression of PRPS2 in tumor cells and observed a significant impact on macrophage migration and MDSC number." (PMID 38952044, 2024). "The function of PRPS2 silencing on tumor growth in vivo was studied through xenograft tumor experiment." (PMID 38736292, 2024). "In order to validate our in vitro findings, we conducted an in vivo animal study to further investigate the role of PRPS2 in tumor development." (PMID 38952044, 2024). "On day 35, the tumor growth index of the control group was higher than that of the PRPS2 knockout group." (PMID 38736292, 2024). "The study on PRPS2 also showed that the expression of hPRPS2 driven by Myc interacted with mTOR, leading to tumor growth." (PMID 37248548, 2023). "TUNEL staining also showed an apoptosis enhancement of tumor cells after PRPS2 knockdown (P < 0.001)." (PMID 31956349, 2020). "c‐Myc gene which is typically overexpressed in BL can regulate the metabolic changes of tumour cells by driving PRPS2." (PMID 32391636, 2020). "The most important genetic characteristic of BL is the amplification of the c‐Myc gene which regulates PRPS2 expression to drive tumour metabolism." (PMID 32391636, 2020). "To evaluate the impact of PRPS2 knockdown on tumor growth in vivo, we established a subcutaneous xenograft tumor model in athymic nude mice by injecting PC‐3 cells infected with shRNA targeting PRPS2 or NC PC‐3 cells." (PMID 31956349, 2020). "Correspondingly, tumor weight in PRPS2 depletion group was lighter than the control group (P = 0.028)." (PMID 31956349, 2020). "Consistently, PRPS2 knockdown suppressed NSCLC tumor growth in vivo." (PMID 42205830, 2026). "Notably, PRPS2 was found to regulate the chemotaxis of TAM and MDSC in tumor cells, as evidenced by the positive correlation of PRPS2 expression levels and abundance of TAM and MDSC populations." (PMID 38952044, 2024). "Interestingly, we observed a significant reduction in the number of macrophages and MDSC in the presence of the CCL2 antibody, suggesting that PRPS2‐mediated regulation of CCL2 in tumor cells plays a crucial role in the chemotaxis of TAMs and MDSC." (PMID 38952044, 2024). "Moreover, IHC results of the xenograft tumor tissues demonstrated that the expression of Ki-67 proliferation antigen in xenografts of sh-PRPS2 cells was significantly decreased (P < 0.001)." (PMID 31956349, 2020). "Moreover, a limited dilution allograft assay using different dosages of 4TO7Lung cells showed that the tumor initiation capacities in the lung was significantly reduced once Prps2 was knocked down." (PMID 33186350, 2020). "Additionally, MYC-driven lymphomagenesis is at least in part dependent upon PRPS2 as Eμ-MYC crossed with PRPS2-null mice have a significant delay in tumor initiation as well as a significant increase in survival." (PMID 28443280, 2017). "The use of clodronate liposomes and anti‐Gr‐1 antibody effectively reversed the phenotypic effects of PRPS2 overexpression, highlighting the significance of TAM and MDSC in mediating the functions of PRPS2 in the tumor microenvironment." (PMID 38952044, 2024). "In conclusion, PRPS2 regulated the chemotaxis of TAM and MDSC in tumor cells by controlling CCL2 expression." (PMID 38952044, 2024). "Our study investigated the role of PRPS2 in regulating the chemotaxis of TAM and MDSC within the tumor microenvironment." (PMID 38952044, 2024).
tumor (continued). "Intriguingly, we also observed a similar trend in CCL2 levels, both at the mRNA and protein levels, in tumor tissues, further confirming the positive correlation between PRPS2 and CCL2 in the LLC tumor tissues." (PMID 38952044, 2024). "Consistent with our in vitro observations, mice implanted with PRPS2 knockdown cells exhibited a significant reduction in tumor volume and weight, concomitant with a decrease in CCL2 levels within the tumor tissues." (PMID 38952044, 2024). "Therefore, PRPS2 may serves as a tumor promoter and a potential new therapeutic target for PCa." (PMID 31956349, 2020). "PRPS2 regulated the chemotaxis of TAM and MDSC in tumor cells by controlling CCL2 expression." (PMID 38952044, 2024). "Our results revealed that mice implanted with PRPS2 knockdown cells displayed an increased percentage of CD4+ and CD8+ T cells, accompanied by a decreased percentage of TAM, M‐MDSC, and PMN‐MDSC within the tumor tissues." (PMID 38952044, 2024). "Importantly, further investigation revealed the phosphorylation at S41 of PRPS2 and at T225 of PRPS1 were all positively correlated with the expression of cell proliferation marker Ki67, confirmed their role in promoting tumor cell proliferation." (PMID 36720864, 2023). "Interestingly, even though the protein abundance of PRPS1/2 was not altered among the tumor, and tumor-adjacent tissues, the T225 phosphorylation of PRPS1 and the S41 phosphorylation of PRPS2 were enhanced in the tumor tissues." (PMID 36720864, 2023).
infection (2 papers, 2018 to 2021). The state of being infected such as from the introduction of a foreign agent such as serum, vaccine, antigenic substance or organism. "We first generated stable PSCs with overexpression of PRPS1 or PRPS2 using lentivirus-mediate infection." (PMID 33493137, 2021).
PRPS2 also shares sentences with these, for which no sentence is quoted: Burkitt lymphoma (2 papers); genetic disorders of (2); hepatocellular carcinoma (2); severe combined immunodeficiency (2); Arts syndrome (1); esophageal carcinoma (1); histiocytic sarcoma (1); hyperuricemia (1); lupus erythematosus (1); mesothelioma (1); metastatic cancer (1); metastatic tumor (1); osteosarcoma (1); pancreatic adenocarcinoma (1); prostate carcinoma (1).